ENSG00000201807
Synonyms: LOC124900226
Gene: Small nucleolar RNA gene on chromosome 6 (136,855,698 to 136,855,831, reverse strand). Ensembl gene ENSG00000201807.
Gene Ontology:
Biological process: RNA processing
Cellular component: nucleolus
Homologues: Paralogues in human: SNORA27 (85% identical).